C5AR1 (complement C5a receptor 1)
Diseases named in the same sentence as C5AR1 in open-access papers (continued):
Sharing a sentence is not in itself a finding about the gene and the disease.
colorectal cancer (10 papers, 2020 to 2026). A primary or metastatic malignant neoplasm that affects the colon or rectum. "In studies on a colorectal cancer model, the C5a/C5aR1 signaling pathway was identified as a factor promoting the accumulation of MDSCs in pathological colorectal tissue." (PMID 39958348, 2025). "As we observed that C5aR1 is expressed in EF5-positive regions in the HCT116 colorectal cancer spheroids, we then examined whether C5aR1 was expressed in BiP (an intrinsic UPR marker)-expressing areas." (PMID 40695778, 2025). "Second, we deleted mono/macrophages and found that deletion of macrophages with anti-CSF1R Ab or clodronate liposomes (CL) ablated the inhibitory effect of anti-C5aR1 Ab on MC-38 colorectal cancer growth in parallel with a decrease in the infiltrated CD8+ T cells." (PMID 38331868, 2024). "In addition, the C5a/C5aR1 axis is also critical for β-catenin stabilization, which is required for the maintenance of stemness in colorectal cancer stem cells." (PMID 38331868, 2024). "qRT-PCR results showed that hypoxia also increases mRNA levels of C5 (which gives rise to C5aR1’s ligand C5a) in an oxygen-dependent manner, with increased expression observed only under severe hypoxia in HCT116 colorectal cancer cells." (PMID 40695778, 2025). "In our investigation, RT-q PCR was utilized to ascertain the expression levels of C5AR1, APOE, CYP1B1, and SPP1 in a standard colon cell line and three colorectal cancer cell lines." (PMID 39494300, 2024). "In this study, it was experimentally confirmed that C5aR1 in CRC cell lines regulates the expression of EMT-related markers E-cadherin and Vimentin, thus affecting the invasion and migration of colorectal cancer cells." (PMID 36192575, 2023). "Moreover, PMX205, a C5aR1 antagonist, blocked AOM-DSS-induced colorectal cancer (CRC) tumorigenesis." (PMID 41300283, 2025). "C5aR1 was involved in EMT process in liver cancer and pancreatic ductal carcinoma, but its relationship with EMT has not been reported in colorectal cancer." (PMID 36192575, 2023).
Hypertension (10 papers, 2017 to 2025). The presence of chronic increased pressure in the systemic arterial system. "C5aR1 was implicated in a model of angiotensin II-induced hypertension." (PMID 31011487, 2019). "Studies showed that biomarkers include PLD2, FLNA (filamin A), SMURF1, LINGO1, CACNA1H, NLRP6, NLRC3, CXCR2 and C5AR1 plays an important role in progression of hypertension." (PMID 36837510, 2023). "As one of the key effector functions, C5a-induced C5aR1 activation, is involved in numerous kidney diseases, but also cardiac remodeling in hypertension, psoriasis, rheumatoid arthritis, complications in sepsis, neuropathic pain, or hidradenitis suppurativa." (PMID 33362783, 2020). "Genetic depletion of C5aR1 or pharmacologic inhibition of C5aR1 diminished hypertension-induced cardiac inflammation and remodeling." (PMID 31011487, 2019). "Nevertheless, despite local complement playing a role in arteriosclerosis, knockout of C3aR1, C5aR1, and C5aR2 in a hypertension mouse model had no apparent effect on hypertension and cardiac injury." (PMID 40519170, 2025). "Meanwhile, we found that C5AR1, CCL4L2, CCL4, CCL20, CD163, CXCL3, and CXCL12 were only expressed in disease a, suggesting the recruitment of inflammatory factors and promotion of the inflammatory response were both more obvious in hypertension-induced AD." (PMID 35800890, 2022).
malaria (10 papers, 2012 to 2024). Malaria is a serious and sometimes fatal disease caused by a parasite that commonly infects a certain type of mosquito which feeds on humans. "Furthermore, murine experimental malaria in pregnancy induced neurocognitive deficits in the offspring via C5aR1 signaling, which were independent of in utero parasite transfer." (PMID 33613523, 2020).
diabetes (9 papers, 2015 to 2024). "In this study, we noted that diabetes was associated with an increase in the number of C5aR1+ neutrophils in the kidney, which supports the involvement of the complement pathway in the activation of pro-inflammatory neutrophils." (PMID 38902253, 2024). "In this study, we found that valproic acid also attenuated diabetes-induced upregulation of complement genes, such as C5aR1 and C5aR2, in the diabetic kidney, suggesting a new pathway regulated by valproic acid." (PMID 36434087, 2022). "We found that renal cortical Klotho expression is significantly downregulated in diabetes and its expression was restored by the deletion of C5aR1." (PMID 36434087, 2022). "To investigate if C5a is involved in mediating cellular senescence, we looked at cellular senescence markers in our previous long term diabetes models and we found that inhibition of C5aR1 attenuated diabetes-induced cellular senescence in DKD." (PMID 36434087, 2022). "SASP marker, IL-6, was increased in renal cortex of mice with diabetes and its gene expression was significantly decreased by the genetic deletion of C5aR1, in C5aR1 knockout (KO) mice." (PMID 36434087, 2022). "These analyses revealed that a significant proportion of genes associated with these pathways were upregulated in diabetes and downregulated by PMX53, further supporting the involvement of C5aR1 in mediating diabetes-induced cell cycle arrest and senescence." (PMID 36434087, 2022). "In the hippocampus, expression of GR and Creb3, a modulator of GR sensitivity, were consistently reduced in C5aR1 knockout mice, suggesting an overall genotype-specific alteration in sensitivity to glucocorticoids, a phenotype also observed in patients with diabetes." (PMID 38628385, 2024). "Similarly, previous studies from our laboratory underscore the protective benefit achieved by disrupting the C5a/C5aR1 signaling axis in murine models of diabetes." (PMID 37240105, 2023). "Furthermore, valproic acid attenuated diabetes-induced upregulation of C5ar1 and C5ar2 expression, concomitant with a downregulation of cellular senescence markers." (PMID 36434087, 2022). "In our study, loss of Klotho in the diabetic setting was restored in mice lacking C5aR1 expression or function in our long-term diabetes model of 24 weeks." (PMID 36434087, 2022). "Conversely, prolonged stress exposure in mice lacking C5aR1 promoted significant hyperinsulinemia and impaired glucose mobilization, an indicator of metabolic dysfunction observed prior to insulin resistance in the early development of diabetes." (PMID 38628385, 2024). "Interestingly, further examination of mice lacking the C5a receptor 1 (C5aR1) gene revealed that cellular senescence was attenuated in diabetes." (PMID 36434087, 2022). "In addition, in the absence of C5ar1, oxidative stress and renal inflammation were attenuated in diabetes as reflected by reduced urinary 8-isoprostanes, and reduced infiltration of tubulointerstitial macrophages, as well as a restoration of the anti-inflammatory regulatory T cells (Tregs)." (PMID 34806406, 2022).
glomerulonephritis (9 papers, 2012 to 2025). A renal disorder characterized by damage in the glomeruli. "However, in the murine model of MPO-ANCA-induced glomerulonephritis, blocking of C5aR1 with a small molecule antagonist (avacopan) is protective, whereas lack of C5aR2 lead to aggravated disease." (PMID 29686675, 2018). "Similarly, C5aR1 is expressed scarcely, whereas expression of C5aR2 is upregulated in MPO-ANCA+ glomerulonephritis." (PMID 29686675, 2018).
psoriasis (9 papers, 2014 to 2023). An autoimmune condition characterized by red, well-delineated plaques with silvery scales that are usually on the extensor surfaces and scalp. "To determine the importance of the C5aR1 signaling pathway in psoriasis, we used C5aR1-deficient mice." (PMID 31447855, 2019). "C5aR1 deficiency or treatment with C5a receptor 1 antagonist (C5aR1a) in mice significantly attenuated psoriasis-like skin lesions and expression of inflammatory cytokines and chemokines." (PMID 31447855, 2019). "However, the role and underlying mechanisms of the complement C5a/C5aR1 signaling pathway in the pathogenesis of psoriasis remain unclear." (PMID 31447855, 2019). "According to previous reports, glycogen phosphorylase (PYGL) and complement component 5a receptor (C5aR1) promote the inflammatory response in psoriasis." (PMID 37226132, 2023). "Altogether, we demonstrate that the C5a/C5aR1 pathway is critical for pDCs functions during the development of psoriasis in mice." (PMID 31447855, 2019). "All these results suggest that C5aR1 signaling pathway is closely related to the pathogenesis of psoriasis." (PMID 31447855, 2019). "All these results indicating that C5a/C5aR1 signaling pathway is essential for early pDCs accumulation in local skin during the development of psoriasis." (PMID 31447855, 2019). "Similar results were observed in patients with psoriasis, as the frequency of C5aR1+ pDCs (CD123+ cells) substantially increased in both local skin tissues and PBMCs, compared to healthy individuals." (PMID 31447855, 2019). "To validate the function of C5aR1 signaling in the pathogenesis of psoriasis, we inhibited the C5aR1 signaling pathway using a C5aR1 peptide antagonist (C5aR1a)." (PMID 31447855, 2019). "Our results provide direct evidence that C5a/C5aR1 signaling plays a critical role in the pathogenesis of psoriasis." (PMID 31447855, 2019). "The C5a/C5aR1 axis is involved in multiple inflammatory diseases, including allergic asthma, rheumatoid arthritis, inflammatory bowel disease, systemic lupus erythematosus, psoriasis, ischemia reperfusion injury, and sepsis." (PMID 33606748, 2021). "Interestingly, IMQ-induced psoriasis-like skin inflammation and total mPASI scores of C5aR1−/− mice were significantly less than those of C5aR1+/+ mice." (PMID 31447855, 2019). "However, the role of the C5a/C5aR1 signaling pathway in pDCs function in the pathogenesis of psoriasis is unknown." (PMID 31447855, 2019). "Furthermore, C5a/C5aR1 signaling potentiated pDCs, monocytes and neutrophils recruitment, and pDCs differentiation and functions, which suggest a possible mechanistic contribution of C5a/C5aR1 signaling in the pathogenesis of psoriasis, that requires further investigation in the future." (PMID 31447855, 2019). "In our study, we observed that expression of complement component 5a receptor 1(C5aR1) was significantly increased in skin lesions of both imiquimod (IMQ) and IL23-induced psoriatic mice and patients with psoriasis." (PMID 31447855, 2019).
Stroke (9 papers, 2020 to 2025). Sudden impairment of blood flow to a part of the brain due to occlusion or rupture of an artery to the brain. "Inhibition of C3aR or C5aR1 is frequently associated with neuroprotection against injuries, such as stroke." (PMID 33613523, 2020). "Mice lacking C5aR1 have displayed smaller infarct sizes after stroke and have better neurological outcomes than their WT controls." (PMID 33239010, 2020). "However, DRD2 and C5aR1 are absent or negligible in marmoset reactive astrocytes with only ESR1 & IL6ST significantly upregulated 1-week after stroke." (PMID 34824275, 2021). "This supports that inflammation triggered by C5a-C5aR1 interactions may promote ischemic injury, but C5b-9-induced cell lysis does not substantially contribute to stroke pathology." (PMID 33239010, 2020). "Meanwhile, C5AR1 inhibitors have significant neuroprotective effects and notably inhibit neuro-inflammation and apoptosis in primary cortical neurons and MCAO-induced stroke models." (PMID 38650649, 2024).
acute kidney injury (8 papers, 2016 to 2026). Sudden and sustained deterioration of the kidney function characterized by decreased glomerular filtration rate, increased serum creatinine or oliguria. "Complement factor 5a (C5a) interaction with its receptor (C5aR1) contributes to the pathogenesis of inflammatory diseases, including acute kidney injury." (PMID 27370410, 2016).
allergic asthma (8 papers, 2017 to 2025). A asthma with a basis in a pathological type I hypersensitivity reaction. "In an OVA-driven allergic asthma model in the rat, the mRNA encoding for C5aR1 was reported to increase in the whole lung upon OVA challenges." (PMID 28231307, 2017). "More precisely, the available data suggest that the C5a/C5aR1 signaling axis controls allergic asthma at the DC/T cell interface." (PMID 31991941, 2020). "Pharmacological targeting of C5aR1 during the sensitization phase increases the severity of the asthmatic phenotype, while targeting of C5aR1 during the effector phase reduces the allergic asthma phenotype." (PMID 28931049, 2017). "We used WT and floxed GFP-C5aR1 reporter mice (GFP-C5aR1flox/flox) in a model of OVA-driven allergic asthma and assessed C5aR1 expression in myeloid and lymphoid cells isolated from the airways, lung tissue and mLN." (PMID 28231307, 2017). "In summary, our findings demonstrate a complex regulation of C5aR1 in eosinophils, macrophages CD11b+ cDCs and moDCs in the effector phase of allergic asthma." (PMID 28231307, 2017). "Next, we determined the impact of C5aR1 deletion in LysM-expressing cells for the development of experimental OVA-driven allergic asthma." (PMID 28931049, 2017). "This is supported by the observations that upon allergic asthma conditions, the expression of C5aR1 is increased in eosinophils." (PMID 28931049, 2017). "C5a regulates the development of experimental allergic asthma during allergen sensitization and the effector phase through activation of its two cognate receptors C5aR1 and C5aR2." (PMID 28231307, 2017). "Here, we performed a precise expression profiling of C5aR1 during the effector phase of experimental allergic asthma." (PMID 28231307, 2017). "Our previous findings demonstrated that the C5a/C5aR1 signalling axis is instrumental for the development of the allergic asthma phenotype." (PMID 28231307, 2017). "The C5aR1 expression and activation on defined innate and adaptive immune cells in established allergic asthma is ill-defined." (PMID 28231307, 2017). "Here, we used these two mouse strains as tools to delineate the impact of C5aR1-specific deletion in LysM-expressing cells on the development of different characteristics of allergic asthma." (PMID 28931049, 2017). "We show that this mouse strain proves useful to determine the impact of C5aR1 on the pulmonary recruitment of LysM-expressing cells and the development of allergic asthma." (PMID 28931049, 2017). "While the expression pattern of C5aR1 in pulmonary cells at steady state is relatively clear, the regulation of C5aR1 expression under allergic asthma conditions during the effector phase remains elusive." (PMID 28231307, 2017). "Future studies using Cre deleter rmice that will allow specific deletion of C5aR1 in bona fide cDCs, eosinophils, basophils, or mast cells will help to broaden our understanding of how the C5a/C5aR1 axis regulates allergic asthma development." (PMID 28931049, 2017). "Since C5aR1 is still expressed in LysM-C5aR1 KO eosinophils, our data suggest a role of eosinophilic C5aR1 in the development and/or severity of the allergic asthma phenotype." (PMID 28931049, 2017). "In a murine allergic asthma model of inflammation, fluid lavaged from the alveolar space demonstrated decreased neutrophilic and eosinophilic granulocyte accumulation when mice receive anti-C5aR1 treatment." (PMID 41458005, 2025). "Furthermore, anti-C5aR1 treatment reduced the amount of neutrophilic and eosinophilic granulocytes in the bronchoalveolar lavage fluid of a mouse model of allergic asthma." (PMID 33606748, 2021). "Genetic ablation or pharmacological targeting of C5 or C5aR1 during allergen sensitization resulted in aggravation of the allergic asthma phenotype, suggesting that C5aR1 protects from the development of allergic asthma." (PMID 28231307, 2017).
allergic asthma (continued). "Here, we determined the role of C5aR1 signaling in neutrophils, moDCs and macrophages for the pulmonary recruitment of such cells and the importance of C5aR1-mediated activation of LysM-expressing cells for the development of allergic asthma." (PMID 28931049, 2017). "Our findings demonstrate a complex regulation pattern of C5aR1 in the airways, lung tissue and mLN of mice, suggesting that the C5a/C5aR1 axis controls airway constriction and inflammation through activation of myeloid cells in all three compartments in an experimental model of allergic asthma." (PMID 28231307, 2017). "In vivo blockade of C5aR1 during the sensitization phase in OVA- and HDM-induced experimental allergic asthma models resulted in increased levels of Th2 cytokines and an overall increased airway inflammation." (PMID 31991941, 2020). "Here, we used this reporter strain to monitor C5aR1 expression in airway, pulmonary and lymph node cells during the effector phase of OVA-driven allergic asthma." (PMID 28231307, 2017). "Here, we monitored C5aR1-expression in myeloid and lymphoid cells in a model of OVA-driven allergic asthma." (PMID 28231307, 2017). "Our findings demonstrate that C5aR1 is critical for steady state control of alveolar macrophage numbers and the transition of neutrophils from the lung into the airways in OVA-driven allergic asthma." (PMID 28931049, 2017). "Until recently, tools were lacking to determine in situ functions of C5aR1 in specific pulmonary cell types in allergic asthma models." (PMID 28931049, 2017). "Our data show that the conditional depletion of C5aR1 in CD11b+ cDCs did not affect the development of Th2/Th17 cells in the OVA model of allergic asthma, similar to what was reported using C5aR1-/- BMDCs." (PMID 28931049, 2017). "In addition, we demonstrated that the expression of C5aR1 was modulated in eosinophils, AMs and DCs in an OVA-induced allergic asthma model." (PMID 28931049, 2017). "Secondly, we determined whether C5aR1+ and C5aR1− cDCs differ in their potential to differentiate CD4+ T cell into Th2 or Th17 effector cells, both of which mediate the maladaptive immune response in HDM-mediated allergic asthma." (PMID 31991941, 2020). "More specifically, C5aR1 expression was downregulated in airway and tissue alveolar macrophages, CD11b+ conventional (c)DCs and monocyte-derived (mo)DCs but upregulated in eosinophils in an OVA-induced allergic asthma experimental model using GFP-C5aR1fl/fl mice." (PMID 28931049, 2017). "Here, we used C5aR1fl/fl and LysM-C5aR1 KO mice in a model of OVA-driven experimental allergic asthma to assess the impact of conditional C5aR1 deletion inLysM-expressing cells on their recruitment to the airways and the lung tissue and the development of allergic asthma." (PMID 28931049, 2017). "However, C5aR1 activation of LysM-expressing cells plays a surprisingly minor role in the recruitment and activation of such cells and the development of the allergic phenotype in OVA-driven experimental allergic asthma." (PMID 28931049, 2017). "Finally, we demonstrate that C5aR1 activation of LysM-expressing cells does not contribute to the development and severity of allergic asthma." (PMID 28931049, 2017). "Thus, C5aR1 deletion in LysM-expressing cells does not affect the recruitment of pulmonary neutrophils, macrophages, CD11b+ or CD103+ cDCs as well as moDCs in OVA-driven allergic asthma." (PMID 28931049, 2017).
colitis (8 papers, 2013 to 2026). Inflammation of the colon. "A recent study on the inhibition of C5aR1 with nano-encapsulated PMX205 significantly reduced pre-clinical colitis with efficacy comparable to C5aR1-deficient models." (PMID 41252181, 2026). "C5a and C5aR1 have been shown to promote colitis, and pharmacological inhibition of C5a activity by PMX205 is efficacious in preventing DSS-induced colitis in mice." (PMID 37426201, 2023).